STAT3 (signal transducer and activator of transcription 3)
Diseases named in the same sentence as STAT3 in open-access papers (continued):
Sharing a sentence is not in itself a finding about the gene and the disease.
tumor (continued). "VEGF is one of the main regulators of tumor angiogenesis and is regulated by a large variety of transcription factors such as HIF-1, nuclear factor κB (NF-κB), and signal transducer and activator of transcription 3 (STAT3)." (PMID 33352897, 2020). "Current studies suggest that tumour reversion may be related to the PI3K/AKT, STAT3, Notch1, and other pathways, and that exosomes derived from ESCs may play an important role in their signal transduction." (PMID 32588948, 2020). "The increased serum IL-6 activated STAT3/c-MYC signaling in peripheral monocytes, enhanced the transcription of miR-25–3 p, suppressed PTPRO expression, promoted PD-L1 through both JAK2/STAT3/c-MYC and JAK2/STAT1 signaling, and promoted tumor growth by enhancing T-cell exhaustion." (PMID 32581055, 2020). "Mice treated with STAT3-MB-mut + UTMC did not exhibit a significant difference in tumor volume compared to that of untreated control mice at any point during the study." (PMID 33206698, 2020). "Beside these inhibitors, there areother small molecules that affect upstream tyrosine kinase and hence areindirect inhibitors of the STAT-3 signaling pathway, e.g. JSI-124.This molecule suppresses phosphorylation of STAT-3 in tumor cells of humans andmouse by inhibiting upstream kinase." (PMID 32167126, 2020). "The activation of STAT3 and downstream effectors may confer drug resistance by initiating the EMT, suppressing epigenetic tumor suppressor miRNAs and enhancing the expression of antiapoptotic proteins." (PMID 33153193, 2020). "These experiments also helped to show that BP-1-102 treatment represses HMGA1, highlighting that not only does HMGA1 induce STAT3 expression but even STAT3 feeds forward to upregulate HMGA1, leading to an enhanced expression of both genes during tumor progression." (PMID 32503270, 2020). "By regulating STAT3 and VEGF signaling, SH2D5 might be involved in regulating YAP/TAZ activity during tumor angiogenesis." (PMID 33614496, 2020). "In addition, the phosphorylation of STAT3/5 and EGFR, as well as the expression of total EGFR, PKCα, TRIB3, and core pluripotency factors, were reduced in tumor tissue samples from NCI-H1975 inoculated mice treated with SAH-JGZ4." (PMID 32694521, 2020). "By its part, STAT3 is a transcription factor involved in the Janus kinase/signal transducer and activator of transcription (JAK–STAT) signaling pathway whose hyperactivation also leads to tumor progression." (PMID 32604771, 2020). "In the tumor microenvironment, it induces EMT via the activation of the JAK2/STAT3 pathway." (PMID 32268527, 2020). "Tumor volume, lung metastasis, and tumorigenic molecules (VEGF-A, HIF-1α, MMP-9, ICAM-1, VCAM-1, and phospho-NF-κB and phospho-STAT-3) were significantly induced in mice injected with ESM-1-overexpressing 4T1 cells and greatly enhanced in those injected with ESM-1-overexpressing RT-R-4T1 cells." (PMID 32466580, 2020). "The pharmacological inhibition of Jak2/Stat3 leads to an antitumor immune response that enhances the efficacy of chemotherapy, suggesting that the oncogene PTEN is involved in immunomodulation of the tumor microenvironment through SASP." (PMID 32028565, 2020). "Analysis of STAT3 protein expression level on a TMA confirmed that most primary tumours of muscle invasive disease express high level of STAT3 but in this cohort STAT3 failed to be a prognostic marker for survival." (PMID 32046095, 2020). "Moreover, the tumor-immunosuppressed programmed death ligand 1 (PD-L1) is expressed via HIF-1α and STAT3 under hypoxic conditions in lung cancer." (PMID 32823915, 2020). "In addition to the well-established activation of STAT3 in epithelial cells during PDAC progression, tumor cells were also shown to activate this pathway in CAFs as a mechanism to support PDAC cell growth." (PMID 32752017, 2020).
tumor (continued). "To further confirm the field effects of p‐STAT3, Mcm2 + luminal to basal ratio, and MSR1 + cell number, we detected the immunoreactivity of the p‐STAT3 and MSR1 + cell number in the PCa, pericancer tissues near and far from tumor core, and benign tissues." (PMID 32860339, 2020). "There is ample evidence for CD44 expression and signaling in the development of cancer therapy resistance and several publications in various tumor models demonstrate functional crosstalk between CD44 and STAT3 (signal transducer and activator of transcription 3)." (PMID 33335857, 2020). "Moreover, CSC uses ALDH to survive chemotherapy by blocking signal transducer and activator of transcription 3 (STAT3)–nuclear factor kappa B (NF-κB) signaling, a pathway that can diminish the accumulation of ALDH1A1 and sensitize tumor cells to chemotherapy." (PMID 32391048, 2020). "The TF–target gene network analysis uncovered an unexpected scenario where both correlation-enhancing genes (with higher correlation in the tumor) and -repressing genes (with lower correlation in the tumor) were targeted by STAT1 (6A), STAT3 (6B), KDM1A (6C), PML and RELA." (PMID 33384992, 2020). "In this process, the expression of downstream MEK1 target genes, such as ERK1/2, STAT3, and JNK were upregulated, which may responsible for the tumor angiogenesis and metastasis of ccRCC." (PMID 32382017, 2020). "The subsequent investigation of S1PR1 revealed that it might also be a prognostic gene in LUAD (in TCGA cohort and GSE72094), with interactions with some well-known tumor genes such as AKT1, STAT3 and CXCR4." (PMID 33628734, 2020). "One such survival mechanism that could occur through IRAK-M is the induction and stabilization of the STAT3 pathway, which is critical for CRC cell survival and tumor progression." (PMID 32533049, 2020). "Given to Stat3 is negative regulated by STING in macrophages, we wondered whether this relationship also exists in tumor cells." (PMID 33288772, 2020). "Similarly, approximately 55.17% of the tumor samples with high TLR9 expression showed strong p-STAT3 (Tyr705) staining, and 75.61% of those with low TLR9 expression showed weak p-STAT3 (Tyr705) staining (p < 0.001)." (PMID 32483468, 2020). "Overall, SG-1721 has been conclusively found to significantly inhibit tumor growth without exhibiting any side effects and negatively regulate STAT3 activation in TNBC models." (PMID 31058868, 2019). "Recently, there were more emerging data about negative and positive regulation of miRNAs networks and JAK/STAT3 signaling pathways via direct and/or indirect regulatory mechanisms in tumor microenvironment." (PMID 31413755, 2019). "However, later studies correlated OSM-OSMR signaling with robust STAT3 and STAT5 activation and more aggressive tumor phenotypes." (PMID 31684144, 2019). "By stratifying samples into STAT3 activity-high (STAT3 activity score > 0) and -low (STAT3 activity score < 0) groups, we indeed confirmed that high STAT3 activities conferred poor prognosis, irrespective of tumor compartment." (PMID 31796877, 2019). "Moreover, macrophages derived from conditional STAT3 knockout mice are better than wild-type macrophages to prime cognate CTL responses and to cross-present tumor-derived antigen to CTLs in vitro." (PMID 31480382, 2019). "Peritoneal tumor analysis showed that the number and weight of metastatic nodules were increased by STAT3-C and STAT3-WT, but decreased by STAT3-DN transfection compared with mice injected with cells expressing PCDH-Vector." (PMID 31597912, 2019). "The results showed that the phosphorylation of ERK1/2 and STAT3 was up-regulated, whereas a lack of CXCR2 suppressed the activation of ERK1/2 and STAT3 in the tumor conditions." (PMID 31395859, 2019).
tumor (continued). "Moreover, IL-6, phosphorylated STAT3 and STAT3 transcriptional activity were consistently upregulated in tumor-spheres from ESE3/EHF under-expressing tumor cells, in line with aberrant activation of IL-6/JAK/STAT3 pathway in prostate CSC." (PMID 31143708, 2019). "This was corroborated by co-localization of STAT3 and STAT1 in DFTD tumor cells." (PMID 30645971, 2019). "In contrast, the cardiomyocyte-restricted deletion of STAT3 did not prevent tumour-induced cardiac dysfunction or the cardiac atrophy phenotype." (PMID 31667271, 2019). "Our data suggested that p-STAT3 inhibition by AG-490 effectively reduced the osteolytic activity of BoM-1833 cells and the following release of TGF-β from bone matrix, thus inhibited the tumor growth." (PMID 31040267, 2019). "STAT3 activation may confer drug resistance by initiating epithelial-mesenchymal transition (EMT), suppressing epigenetic tumor suppressor microRNAs (miRNAs) and enhancing the expression of antiapoptotic proteins." (PMID 30927928, 2019). "Constitutive signal transducer and activator of transcription 3 (STAT3) activation has been correlated to metastasis, poor patient survival, larger tumor size, and acquired resistance against vemurafenib (PLX-4032), suggesting its potential as a molecular target." (PMID 30691132, 2019). "Along with the role of JAK/STAT in driving normal cellular processes, STAT3, and to a lesser extent STAT5, are well defined contributors to tumor cell growth, while also promoting inflammation within the tumor microenvironment that supports disease progression." (PMID 31409327, 2019). "To show that the inferred compartment-specific STAT3 scores indeed reflected regulatory activities in tumor cells or the TME, rather than capturing tumor purity, we examined their correlation with tumor purity." (PMID 31796877, 2019). "Furthermore, both STAT3 and HIF-1α are responsible for the metabolic shift toward aerobic glycolysis, known as Warburg effect, which is typical of highly aggressive tumours." (PMID 31013746, 2019). "Several lines of evidence have highlighted the role of STAT3/5 activation in non-malignant somatic cells of the EOC tumor microenvironment and the crosstalk between tumor and host stromal cells." (PMID 31861720, 2019). "In addition, IL-6 promotes the proliferation and survival of tumor cells, as well as angiogenesis, by regulating Janus kinase (JAK)/STAT3 signaling pathways." (PMID 31500658, 2019). "Subsequently, we examined the potential target(s) for miR-21-5p using bioinformatics tools and we identified STAT3, a well-known oncogene, and PDCD4, an established tumor suppressor, as the top-ranking candidates from all three algorithms used (PITA, miRmap, and miRanda)." (PMID 31269723, 2019). "Evidence suggests that an increase in STAT3 may up-regulate the expression of VEGF and other factors, thereby promoting angiogenesis and promoting tumor growth and metastasis." (PMID 30651572, 2019). "Strikingly, a study reported that cigarette smoking induced the secretion of exosomes containing miR-21 from bronchial cells, enhancing VEGF levels through STAT3 deregulation in Human Bronchial Epithelial Cells (HBEC) and promoting angiogenesis and tumor growth." (PMID 31242686, 2019). "FEZF1-AS1 can activate EMT of tumor cells through Wnt/ β-catenin and JAK2/STAT3 signaling pathways." (PMID 31175144, 2019). "For instance, CD44v isoform, an alternative splicing variant of CD44 containing v8–v10 exons, was convinced to drive tumor progression and metastasis by promoting BRCA stemness via activating the PDGFRβ/Stat3 cascade and PFKFB4-mediated glucose metabolism despite tumor-suppressing genetic origin." (PMID 30984247, 2019). "Furthermore, we analyzed the protein expression of STAT3 and mTOR in 12 pairs of CRC tumor and matched adjacent normal tissues by western blot analysis." (PMID 31287013, 2019). "In contrast, STAT3 signaling pathways can also inhibit MMP expression and tumor metastasis." (PMID 30651572, 2019).
tumor (continued). "The STAT3 signaling pathway also plays an important role in recruiting and promoting the proliferation of Tregs, which in turn has suppressive activity toward CD8+ effector T cells and other immune cell types within the tumor microenvironment." (PMID 31775797, 2019). "We also found treatment with TCM derived from the MC38-exS1PR1 group induced strong S1PR1 and p-STAT3 activation in MDSCs without tumor cell challenge compared to the MC38-exControl group and untreated group." (PMID 31534132, 2019). "In addition, the co-delivery of nanoparticle-mediated STAT3 siRNA and TLR7/8 agonist or TLR3 agonist enhanced expression of co-stimulatory CD40 and CD86 in DCs, and DCs-mediated anti-tumor immunity." (PMID 30658461, 2019). "Thus, tumor hypoxia led to CD45 protein tyrosine phosphatases activation, resulting in STAT3 activity downregulation and in M-MDSC differentiation into tumor-promoting TAMs." (PMID 31480382, 2019). "It is reported that the STAT3 directly activates MIR21 and MIR181b-1, respectively, suppressing the targets phosphatase and tensin homolog (PTEN) and CYLD (CYLD lysine 63 deubiquitinase) tumor suppressors." (PMID 31075975, 2019). "In preclinical studies, systemic delivery of STAT3 decoy failed to inhibit xenograft tumor growth, presumably due to rapid degradation of the molecule by nucleases in the blood." (PMID 31671769, 2019). "Herein, we demonstrated for the first time that macrophages play an essential role in the potent pro-tumor effect of GC-MSCs; in turn, GC-MSCs induce the polarization of macrophages into the M2 subtype through secreting IL-6 and IL-8 via the JAK2/STAT3 signaling pathway." (PMID 31801938, 2019). "Constitutively active STAT3 regulates expression of genes that are involved in multiple oncogenic processes in ABC DLBCL, including promoting cell survival, proliferation, and migration, reprogramming metabolism and facilitating tumor immune evasion." (PMID 31861597, 2019). "PH potently inhibited tumor growth in both Sor-sensitive and Sor-resistant xenografts in vivo by impairing angiogenesis, cell proliferation and inducing apoptosis via targeting the SHP-1/STAT3 signaling pathway." (PMID 31619257, 2019). "Based on the previously recognized coordination between STAT3 activity in cells of the TME and tumor cells, we were curious if we could assess this interaction with our compartment-specific framework." (PMID 31796877, 2019). "Similarly, STAT3 (signal transducer and activator of transcription 3) is also involved in cell survival and proliferation and the deregulation of STAT3 leads to tumor progression and metastasis." (PMID 31121868, 2019). "Evidences at both transcriptional and translational levels as well as functional studies using established stable cells with FA2H modulation suggested the tumor suppressive roles of FA2H on cancer stemness and cell migration via inhibiting the STAT3/IL6 axis and NFkB mediated signaling." (PMID 31709178, 2019). "Our study also showed that EYA1 is responsible for SIX1-induced STAT3 signaling activation, indicating disruption of EYA1 function may suppress the SIX1-mediate tumor growth in PTC." (PMID 31921695, 2019). "Tumor cell decreases in JAK2 target genes (Socs3, Egfr) were reported, which indicated that target inhibition was achieved, along with decreases in activated STAT3, which was high at trial commencement in all patients." (PMID 31842362, 2019). "No changes in the expression of p-STAT3 or p-STAT5 were observed in whole tumor lysates from these experiments." (PMID 31700995, 2019). "It was also observed that estrogen activates G protein-coupled estrogen receptor-1 (GPER-1), inhibits the expression VEGF at both protein and mRNA levels, and suppresses the tumor growth and angiogenesis in TNBC xenograft tumor models, in which STAT3 is involved." (PMID 31088482, 2019).
tumor (continued). "Besides, the other two molecules, AKT and STAT3, are not only involved in regulating BTLA expression but also modulating several signaling pathways in the process of tumor progression." (PMID 31753019, 2019). "One study has also reported that haptoglobin could participate with STAT3 and HIF-1a in promoting angiogenesis and cell migration, and thus contributes to driving tumour growth and invasion." (PMID 31042781, 2019). "IL-6 and IL-11 activate signal transducer and activator of transcription 3 (STAT3), and this canonical pathway may represent a mechanism by which chronic inflammation contributes to tumour initiation and progression." (PMID 31123345, 2019). "Given that the elevated Stat3 expression was not uniform throughout the tumor and that Stat3 is a critical immune signaling protein we assessed the extent of tumor infiltrating leukocytes." (PMID 31683879, 2019). "Importantly, we demonstrated that LDH@155 synergistically skewed TAMs to M1 subtype in STAT3, ERK1/2, and NF‐κB dependent manner, which led to induce higher T‐cell activation and inhibit MDSCs infiltration in tumor environment." (PMID 31016114, 2019). "Furthermore, leelamine has been shown to target key oncogenic pathways (RTK–AKT/STAT3/MAPK, AKT/mTOR) in various tumor cells." (PMID 31330969, 2019). "Combined inhibition of STAT3 and p38 MAPK could prevent tumor-mediated suppression of monocyte-derived DC differentiation." (PMID 30987665, 2019). "The STAT3 expression difference has not been found between patients of different ages or tumor sizes." (PMID 31375715, 2019). "In summary, LINC00857 influenced tumor cell proliferation, colony formation, apoptosis, as well as migration and invasion which may be via affecting MET/STAT3/c-Myc/CREB oncoproteins." (PMID 31085800, 2019). "Collectively, brevilin A displayed an anti-tumor effect against HCC in vitro, which might be attributed to the inactivation of Stat3/Snail and Wnt/β-catenin signaling pathways." (PMID 35547606, 2019). "Taken together, LINC00857 affecting tumor cell proliferation, colony formation, apoptosis, as well as migration and invasion may be via MET, STAT3, c-Myc and CREB oncoproteins." (PMID 31085800, 2019). "Moreover, Kaempferol alone or combined with 5-FU reduced the phosphorylated form of STAT3 and the one of the pro-survival kinase AKT and its target tumor suppressor FOXO3a transcription factor, in both sensitive and resistant tumor cells." (PMID 30655588, 2019). "Importantly, we provided evidence that AZD1480 (in STAT3-high GBM cells) and AZD1480/Linsitinib (in STAT3-low GBM cells) synergized with TMZ to mitigate in vitro tumor cell viability." (PMID 31399589, 2019). "Furthermore, rescue of STAT3 expression in the miR‐125b‐5p cotransfected cells recovered virtually all of the CSC, as indicated by the resu med proportion and tumor sphere formation potency." (PMID 31065520, 2019). "Here we investigated the antitumor effects of novel pyrazole-based STAT3 pathway inhibitors named MNS1 (Mayo Neurosurgery 1) in both pediatric and adult HGG tumor cells." (PMID 31361777, 2019). "Several downstream effectors of STAT3 in tumor cells were reported to contribute to non-cell-autonomous resistance to antineoplastic treatment." (PMID 30927928, 2019). "STAT1 and STAT3 activation are critical for these Tfh-like cell induction which operate via IL-21-IFN-γ pathways to induce plasma cells and create conditions for M2b macrophage polarization and tumor growth." (PMID 31480382, 2019). "One of the previous publications suggested that the expression of STAT3 in its phosphorylated form is not related to tumor localization, which is contrary to the results of our study." (PMID 31234597, 2019). "Phospho‐STAT3 positivity, defined as expression in ≥ 17% of tumor cells, was not exclusively, but much more commonly found in ABC‐DLBCL tumors, and in more advanced (stage 3 and 4, relative to stage 1 and 2) disease." (PMID 31515941, 2019).